TTR (transthyretin)
Diseases named in the same sentence as TTR in open-access papers (continued):
Sharing a sentence is not in itself a finding about the gene and the disease.
tumor (continued). "For OS, univariate analysis showed that narrow tumor margin, high recurrent AFP level, larger recurrent tumor size, and early recurrence showed association with shorter OS (all P < 0.05), while initial AFP level, tumor margin, MVI, and TTR were shown to be as independent risk factors of OS." (PMID 34127007, 2021). "Besides such evidences from histopathology, tissue physiology and artificial organ approaches it has been reported that blood released protein factors like transthyretin (TTR) can act as reliable serum tumor markers." (PMID 30836676, 2019). "A test of interaction between the prognostic effect of higher ERCC1-19q13/CEN-2 ratios tumor localization approached significance (p = 0.07 with TTR as endpoint), and therefore the multivariate analysis (adjusting for age and gender) was performed separately for each localization." (PMID 24144331, 2013). "Presence of TTR in tumor tissue was determined with indirect peroxidase immunostaining." (PMID 16225703, 2005). "Because TTR protein has been linked to tumor growth and severity, His90Asn associations observed in our study may be related to the effect of this mutation on TTR function rather than on the amyloidogenic cascade." (PMID 38523305, 2024). "Interestingly, in patients with high Cripto-1 expression, the results showed that without received TACE (P = 0.019), larger tumor size (P = 0.01), multiple tumor (P = 0.001), satellite nodule (P = 0.025) and vascular invasion (P = 0.005) were unfavourable factors for TTR in HCC patients." (PMID 31136302, 2019). "For chromatin accessibility data of scCPA‐Tag, the cluster exhibiting high gene activity scores for ALB, TTR, and APOA2 was identified as tumour cell." (PMID 39210544, 2024). "Since we have previously proved the efficiency of the TTR-Cre-ERT2 system, we reasoned that such tumor nodules were escapers." (PMID 39325536, 2024). "After interfering with the TTR expression of HCCC9810, the tumor cells were co‐cultured with THP‐1 + TNF‐α." (PMID 37688511, 2023). "Evidence suggested that transthyretin (TTR) influenced the prolifetation and invasion functions of different tumors and play an essential role in the tumor microenvironment." (PMID 37688511, 2023). "The upregulated expression of these miRNA was found to be identical to the downregulated expression of AHSG, F2, and TTR, thereby proving the potential miRNA-dependent regulation of AHSG, F2, and TTR expressions in tumor samples." (PMID 36224755, 2022). "High transthyretin observed at D28 was concomitant with the elimination of the immature malignant clones in both PB and BM in all patients, suggesting that its augment could represent an additional marker for tumor cell elimination during the B-ALL induction phase treatment." (PMID 33381445, 2020). "In addition to assessing clinical symptoms at admission, blood tests were performed to measure serum Alb (g/dL), TTR (mg/dL), CRP (mg/dL), and tumor markers." (PMID 41181583, 2025). "Immunostaines for RCC, CD10, CK20, chromogranin A, synaptophysin, TTF-1, thyroglobulin, and transthyretin were negative in the tumor cells." (PMID 30340515, 2018). "Here, we show that conditional (TTR-Cre) hepatocyte-specific SMAD7 knockout (KO) mice develop more tumors than wild-type and corresponding SMAD7 transgenic mice 9 months after diethylnitrosamine (DEN) challenge, verifying SMAD7 as a tumor suppressor in HCC." (PMID 28134936, 2017). "This is further supported by the observation that the tumor site itself does not express any immunoreactive TTR." (PMID 16225703, 2005). "Neither TTR nor its truncated form originates from tumor tissue and its occurrence in ascites may well reflect the filtration from blood into ascitic fluid." (PMID 16225703, 2005). "The derivatization with the transthyretin binder also did not affect the target-specific cell uptake, which remained high in the PSMA-positive PC-3 PIP tumor cells, while only negligible uptake was seen in PSMA-negative PC-3 flu cells." (PMID 38610940, 2024).
tumor (continued). "The tumor cells were negative for CK20, synaptophysin, chromogranin A, transthyretin, TTF-1, RCC, thyroglobulin, and CD10." (PMID 30340515, 2018).
infection (48 papers, 2010 to 2025). The state of being infected such as from the introduction of a foreign agent such as serum, vaccine, antigenic substance or organism. "The cells also expressed the CPE marker transthyretin and are as susceptible to infection with purified JCPyV virions as the parental primary cells and the human T-antigen transformed glial cell line, SVG-A." (PMID 32130281, 2020). "Unfortunately, risk factors for MDR and non-MDR infections are similar, and their correction often requires a longer hospital stay which in turn is another risk factor for MDR infections (e.g. as it is in our series for low transthyretin levels associated to MDR-Os-SSI in multivariate analysis)." (PMID 35304900, 2022). "Inflammation or infection can dramatically inhibit the production and release of TTR in the liver, leading to a decrease in serum TTR levels." (PMID 37626934, 2023). "Transthyretin can well reflect the malnutrition status of the body, we supposed that decreased transthyretin might cause chemotherapy resistance, decrease autoimmune function, increase the change of serious infection, and finally shorten the survival of the MDS patients." (PMID 36960201, 2023). "We still found infection exclusively of the ChP in these conditions, as also confirmed by co-staining for the ChP marker TTR, suggesting that also live SARS-CoV-2 specifically infects the ChP." (PMID 33113348, 2020). "Among them, 25 genes, such as arachidonate 15-lipoxygenase (ALOX15), collagen, type VI, α5 (COL6A5), and serglycin (SRGN), were significantly upregulated while the expression of transthyretin (TTC) was repressed by infection." (PMID 27197554, 2016). "Nonetheless, proportions of NP396–404-specific CD8+ T cells were reduced in both the spleen and liver of TTR-NP mice compared with B6 mice at 8 and 55 days after infection." (PMID 28210682, 2015). "Eight days after LCMV-WE infection, the number of splenic Tregs in B6 mice decreased slightly while their numbers remained elevated in infected TTR-NP mice." (PMID 28210682, 2015). "Cytokine-producing LCMV-specific CD8+ T cells were reduced in the spleen of TTR-NP mice compared with B6 mice 55 days after infection." (PMID 28210682, 2015). "Beginning on day 8 and increasing until day 55 after infection, TTR-NP mice showed high PD-1 expression on CD8+ and CD4+ T cells." (PMID 28210682, 2015). "The LCMV titers in infected TTR-NP mice were higher on day 8 than in B6 mice and remained high in the spleen, liver, and kidney for over 147 days after infection." (PMID 28210682, 2015). "Fifty-five days after infection, the serum levels of IL-10 were statistically significantly higher in the infected TTR-NP mice than in the B6 mice and remained elevated up to 147 days after infection." (PMID 28210682, 2015). "Recent studies suggest that TTR may also participate in modulating uterine immune responses under conditions of stress or infection, as elevated TTR concentrations have been detected in uterine fluid of mares subjected to infection or corticosteroid treatment." (PMID 41049139, 2025). "Decreased plasma CRTAC1 could result from decreased production as occurs with ALB and TTR, increased turnover as occurs during severe infection with GSN serving as a scavenger for filamentous actin being released from cells, or a combination of mechanisms." (PMID 37667413, 2023). "Transthyretin was hypothesized to be secreted by M. incognita to regulate host plant cell growth, contribute to establishment of infection and participate in immune evasion." (PMID 34587193, 2021). "By day 19 post infection, serum TTR levels had increased 11-fold over controls." (PMID 33986266, 2021). "Consider the following sentence from the PPI corpora: “We took advantage of previously collected data during a randomized double-blind, placebo-controlled clinical trial to conduct a secondary analysis of the RBP/TTR ratio and its relationship to infection and VA status.”." (PMID 29382397, 2018).
infection (continued). "Indeed, we detected the serum protein transthyretin in BAL-f of ExoY-infected mice already at 4 h after infection, indicating a compromised blood-air barrier." (PMID 29734720, 2018). "Studies that have defined metabolic biomarkers in serum of experimentally infected cattle have demonstrated that infection results in decreased energy and increased protein turnover, as well as vitamin D binding protein precursor, transthyretin, retinol binding protein, and cathelicidin." (PMID 27093613, 2016). "The infection persisted for at least 147 days in TTR-NP mice." (PMID 28210682, 2015). "The TTR-NP mice showed a significant increase in the proportion of CD4+ FoxP3+ T cells among the CD4+ T cells after infection with LCMV-WE or LCMV-Arm compared with the B6 mice in both the spleen and liver, and they remained elevated throughout the chronic infection." (PMID 28210682, 2015). "Furthermore, some of the DEG transcripts we found are present also in blood (hemoglobin, transthyretin, serpin peptidase inhibitor) and among them hemoglobin exhibited decreased expression throughout the entire course of the infection, including preclinical time points, in mouse models." (PMID 24898206, 2014). "One week after infection, the same mice were HDTV injected with the TTR > NICD-CAG>tdT transposon to induce plastic states in tdT+ hepatocytes." (PMID 41290681, 2025). "The number of CD4+ regulatory T cells before infection was similar between TTR-NP1/0 and TTR-NP mice in both the spleen and liver." (PMID 28210682, 2015). "Eight days after infection, proportions of NP309–328-specific CD4+ T cells were also reduced in both the spleen and liver of TTR-NP mice compared with B6 mice." (PMID 28210682, 2015). "Our data indicate that only IN boosting ensured clinical protection against high-dose infection, whereas even three doses of the subcutaneous TTR fusion vaccine did not." (PMID 41270167, 2025). "Since LSEC do not express OVA after infection with the TTR-driven adenovirus, this data provide strong evidence for cross-presentation of viral antigen from infected hepatocytes by LSECs, which then become targets for CTL-mediated attack." (PMID 30442932, 2018). "During the acute phase of infection, there is an increase in plasma acute phase proteins including Hp, AGP, serum amyloid A, and Pig major acute phase protein, accompanied by a decrease in the plasma level of TTR." (PMID 27741252, 2016). "Following Streptococcus suis type-2 infection TTR showed a negative APR with serum concentrations reaching a significantly lower level at 2 days following infection." (PMID 21430962, 2011). "Similarly, levels of Transferrin, Afamin, Fetuin A (Alpha-2-HS Glycoprotein), Fetuin B and Transthyretin were reduced in both infection types, and no statistical difference was found between their levels." (PMID 30774579, 2019). "Plasma retinol concentration may also be low during inflammation or infection because of transient decreases in the concentrations of the negative acute phase proteins, retinol binding protein, and transthyretin, even when liver retinol is adequate." (PMID 30213044, 2018). "Interestingly, transthyretin was detectable in the BAL-f of ExoY-infected mice as early as after 4 h post infection, but was not detectable in significant amounts in ExoYK81M-infected mice until 24 h after infection." (PMID 29734720, 2018). "However, TTR-NP mice are not immunodeficient and mount efficient antiviral T- and B-cell responses against vesicular stomatitis virus and clear infection (data not shown)." (PMID 28210682, 2015). "However, although the GP33–41-specific proliferation was similar between TTR-NP and B6 mice, NP396–404-specific proliferation was increased in TTR-NP mice, suggesting that NP396–404-T cells are not anergic at early stages of infection." (PMID 28210682, 2015).
neurodegenerative disease (42 papers, 2010 to 2025). A disorder of the central nervous system characterized by gradual and progressive loss of neural tissue and neurologic function. "ZK697.8 encodes the protein transthyretin, which is associated with neurodegenerative diseases and has been reported to negatively regulate lifespan in Drosophila." (PMID 36670987, 2023). "These pathogenic responses to toxic TTR species are similar to those observed in other neurodegenerative diseases." (PMID 24459092, 2014). "Familial amyloidotic polyneuropathy (FAP) is a neurodegenerative disease caused by the extracellular deposition of mutant transthyretin (TTR), with special involvement of the peripheral nervous system (PNS)." (PMID 22253829, 2012). "In addition to the diagnostic information the possibility of using TTR as a CSF oxymeter is of potential value in studies monitoring disease activity and developing new drugs for neurodegenerative diseases." (PMID 24678637, 2014). "Furthermore, several proteins linked to neurodegenerative diseases, such as amyloid beta, tau, prions and transthyretin, were found to be glycated in patients, and this is thought to be associated with increased protein stability through the formation of crosslinks that stabilize protein aggregates." (PMID 21044301, 2010). "TTR was described as the major binding site for Aβ in the CNS, and a protective role for it against neurodegenerative diseases and AD was postulated." (PMID 39192044, 2025). "In summary, the data suggest a multifaceted and clinically protective role of TTR in several neurodegenerative diseases." (PMID 40717228, 2025). "Based on these observations, we propose the novel potential of thyromimetics as a multi-functional therapeutic molecule for TTR-related pathologies, including neurodegenerative diseases." (PMID 33800546, 2021). "Pro-oxidation is a feature in the pathophysiology of many neurodegenerative diseases including TTR amyloidogenesis." (PMID 30934952, 2019). "Tafamidis reduces TTR amyloid and soluble misfolded TTR assemblies in FAP, and remains the only therapeutic for a neurodegenerative disease that specifically targets the underlying causative amyloidogenesis." (PMID 29654159, 2018). "Familial amyloidotic polyneuropathy (FAP) is an autosomic dominant neurodegenerative disease characterized by the formation of amyloid fibril deposits, mainly composed of transthyretin (TTR), in different organs and tissues." (PMID 22053176, 2011). "In summary, TTR may act as a neuromodulator and aid important cognitive functions, such as learning and memory, while offering clinical protection from neurodegenerative disease." (PMID 40717228, 2025). "Proangiogenic properties of TTR may be another mechanism by which it can moderate neurodegenerative disease." (PMID 40717228, 2025). "TTR-FAP is a life-threatening neurodegenerative disease that constitutes a public health problem in Majorca, with a disease focus growing mainly due to TTR-FAP is being better understood so patients could be diagnosed earlier." (PMID 24572009, 2014). "Although C. elegans has been widely employed to investigate a number of neurodegenerative diseases, its application to the study of systemic amyloidoses related to human proteins, i.e. lysozyme, monoclonal light chains, β2-microglobulin (β2-m) and transthyretin (TTR), is limited." (PMID 23284985, 2012). "A recent preprint suggests that SARS-CoV-2 induces amyloid aggregation of several proteins involved in neurodegenerative diseases such as APLP1, ApoE, clusterin, α2-macroglobulin, PGK-1, ceruloplasmin, nucleolin, 14–3-3, transthyretin, and vitronectin." (PMID 36362302, 2022). "From the candidate list of robustly increased proteins in iron treated worms we also noted several transthyretin (TTR) proteins, which are known to be involved in human neurodegenerative disease." (PMID 25554795, 2014).
neurodegenerative disease (continued). "However, TTR in its pathological form, amyloid transthyretin (ATTR), is responsible for a spectrum of progressive, debilitating, life-altering neurodegenerative diseases known as ATTR amyloidosis which originated from the misfolding, mis-aggregation and systemic deposition of ATTR in several organs." (PMID 31835306, 2019). "With no potential neurodegenerative disease link target, 18alpha-glycyrrhetinic acid can be considered the most potent and specific drug candidate against CST, while in the case of β-carotene, transthyretin and RBP4 may act as cross-targets in the brain." (PMID 39450315, 2024).
autosomal dominant disease (38 papers, 2010 to 2025). Autosomal dominant form of disease. "Hereditary transthyretin amyloidosis (ATTRv) is a rare autosomal dominant disease related to pathogenic genetic mutations in the TTR gene encoding transthyretin, with a current prevalence in Europe estimated between 1/130,000 (France) and 1/675,000 (Germany)." (PMID 40260709, 2025). "As a result, the production of an abnormal form of transthyretin is inhibited (a genetic autosomal dominant disease caused by a mutation in the TTR gene, rapidly progressive, and affecting approximately 50,000 people worldwide)." (PMID 38534656, 2024). "Hereditary transthyretin amyloidosis (ATTRv) is a rare autosomal dominant disease caused by pathogenic variants in the transthyretin (TTR) gene on chromosome 18." (PMID 38399526, 2024). "hATTR-PN is an autosomal dominant disease caused by the accumulation of amyloidogenic transthyretin in organs and tissues, which is mainly the result of the presence of the Val30Met variant in the TTR gene." (PMID 38976223, 2024). "ATTRv is an autosomal dominant disease caused by the extracellular deposition of amyloid fibrils produced by misfolded transthyretin variants." (PMID 36555770, 2022). "Familial amyloid cardiomyopathy (FAC) is a rare autosomal-dominant disease associated to the deposition of TTR amyloid plaques in the myocardium and related to the most common TTR mutation Val122Ile." (PMID 32456156, 2020). "Hereditary transthyretin amyloidosis (ATTRv, v for variant) is a late-onset, autosomal dominant disease caused by progressive extracellular deposition of transthyretin amyloid fibrils, leading to organ damage and death." (PMID 33317601, 2020). "wt-ATTR is characterized by wild-type TTR amyloid deposition, while the latter is a heterogeneous group of autosomal dominant diseases caused by mutation in the TTR gene." (PMID 27122057, 2016). "Transthyretin-associated Familial Amyloid Polyneuropathy (TTR-FAP) is an autosomal dominant disease caused by the deposition of abnormal transthyretin that results from a gene mutation." (PMID 24572009, 2014). "Hereditary transthyretin amyloidosis is a rare autosomal dominant disease characterized by extracellular accumulation of amyloid fibrils composed of the transthyretin (TTR) protein in different organs." (PMID 36365206, 2022). "Hereditary transthyretin amyloidosis (ATTR) is an autosomal dominant disease characterized by the extracellular deposition of the transport protein transthyretin (TTR) as amyloid fibrils." (PMID 34343569, 2021). "Familial amyloidotic polyneuropathy (FAP) is a rare autosomal dominant disease characterised by the deposition of transthyretin (TTR) protein in peripheral nerves." (PMID 21375738, 2011).